SLC11A1 (solute carrier family 11 member 1)
Diseases named in the same sentence as SLC11A1 in open-access papers (continued):
Sharing a sentence is not in itself a finding about the gene and the disease.
mastitis (6 papers, 2017 to 2025). Inflammation of breast tissue during lactation or postpartum due to an obstructed duct or infection. "Our findings are consistent with those of previous findings that have demonstrated the presence of a novel mutation at 1139 bp in exon 11 of the SLC11A1 gene and a significant association of this SNP with clinical mastitis." (PMID 40427248, 2025). "It is noteworthy that SNP in the SLC11A1 gene was identified as a significant genetic marker and susceptibility factor for mastitis tolerance/susceptibility in both Holstein and Swiss Brown cows." (PMID 40427248, 2025). "For the first time, they reported that the mRNA expression of the SLC11A1 gene in mastitis-resistant herds was higher than that in susceptible herds, and cows with high mastitis resistance can be screened based on this difference." (PMID 38066966, 2023). "In addition, the SNP in the SLC11A1 gene was identified as an important genetic marker and susceptibility factor for mastitis tolerance/susceptibility in Holstein and Swiss Brown cows." (PMID 40427248, 2025). "Furthermore, a mutation was identified at 1139bp in exon 11 of the SLC11A1 gene, which was significantly associated with the development of clinical mastitis." (PMID 40427248, 2025). "The bovine SLC11A1 gene has emerged as a focal point of research, particularly as a pivotal candidate gene in investigations pertaining to disease resistance and susceptibility, including ailments such as bovine brucellosis and mastitis." (PMID 38066966, 2023). "It is suggested that SLC11A1 may be a candidate gene associated with mastitis resistance." (PMID 40427248, 2025). "In addition, using PCR-DNA sequencing of immunological (SELL, ABCG2, FEZL, and SLC11A1) markers from the investigated Holstein and Brown Swiss dairy cows, nucleotide sequence alterations in the form of SNPs related to mastitis tolerance/susceptibility were found." (PMID 37756095, 2023). "Thus, SLC11A1 may be a candidate genes associated with mastitis resistance." (PMID 40427248, 2025). "This study provided a theoretical basis for resolving the important role of SLC11A1 in mastitis in dairy cows." (PMID 40427248, 2025). "The three genotypes formed by this point mutation were significantly related to the incidence rate of mastitis in Holstein cows, and this result shows that SLC11A1 is a candidate gene for mastitis resistance." (PMID 38066966, 2023). "The correlation analysis of the different genotypes and the incidence rate of mastitis showed that 6358 (C/T) and 7155 (A/G) of the SLC11A1 gene had significant effects on the number of somatic cells and milk production (p < 0.05)." (PMID 38066966, 2023). "PCR-DNA sequencing of SELL, ABCG2, SLC11A1, FEZL, SOD1, CAT, GPX1, and AhpC/TSA revealed nucleotide sequence variations in the form of SNPs associated with mastitis tolerance/susceptibility in investigated Holstein and Brown Swiss dairy cows." (PMID 35737346, 2022). "In the present study, a real-time PCR was carried out to quantify the mRNA level of SELL, ABCG2, SLC11A1, FEZL, SOD1, CAT, GPX1, and AhpC/TSA genes in tolerant and susceptible Holstein and Brown Swiss dairy cows to mastitis." (PMID 35737346, 2022). "As far as we are concerned, this is the first study revealing SNPs in SELL, ABCG2, SLC11A1, FEZL, SOD1, CAT, GPX1, and AhpC/TSA genes as candidates for mastitis tolerance/susceptibility in Holstein and Brown Swiss dairy cows." (PMID 35737346, 2022). "Since SLC11A1 is involved in innate immunity by killing bacteria, we hypothesized that it is a candidate gene for mastitis resistance." (PMID 40427248, 2025). "Furthermore, a comparison of the transcriptomes of circulating leukocytes from healthy cows with those from cows with naturally occurring subclinical or clinical mastitis revealed some differentially expressed genes, including SLC11A1." (PMID 40427248, 2025).
mastitis (continued). "Finally, we predicted the SLC11A1 protein interaction network and found that SPI1, NOD2, TLR2 and S100A12 interacted with SLC11A1 and were reported as candidate genes associated with mastitis resistance." (PMID 40427248, 2025). "SLC11A1 was closely associated with the expression of genes involved in the regulation of the immune response and inflammation, with S100A12, NOD2, TLR2 and SPI1 being closely associated with mastitis resistance." (PMID 40427248, 2025). "Although, there is little information on SELL, ABCG2, SLC11A1, and FEZL genes polymorphisms and their association with mastitis susceptibility in dairy cattle, previous studies reported these association in one breed using RFLP and SSCP genetic markers with opposing results." (PMID 35737346, 2022). "Although there is little information on SELL, ABCG2, SLC11A1, and FEZL gene polymorphisms and their association with mastitis susceptibility in dairy cattle, previous studies reported this association in one breed using RFLP and SSCP genetic markers with opposing results." (PMID 35737346, 2022). "Consequently, the aim of the current work was to revealing the association of SNPs and expression profile of SELL, ABCG2, SLC11A1, FEZL,SOD1,CAT,GPX1, and AhpC/TSA genes with mastitis tolerance/susceptibility in Holstein and Brown Swiss dairy cows." (PMID 35737346, 2022). "Mastitis resistant dairy cows can be selected according to the difference in SLC11A1 expression." (PMID 32204353, 2020). "Therefore, changes in the structure of SLC11A1 may influence mastitis resistance traits in Holstein cows." (PMID 40427248, 2025). "However, the indirect role of SLC11A1 in mastitis needs to be further investigated." (PMID 40427248, 2025). "Consequently, SELL, ABCG2, SLC11A1, FEZL, SOD1, CAT, GPX1, and AhpC/TSA regulation mechanisms are well understood in the mastitis tolerant and affected Holstein and Brown Swiss dairy cows." (PMID 35737346, 2022).
Sepsis (6 papers, 2010 to 2026). Sepsis is defined as life-threatening organ dysfunction caused by a dysregulated host response to infection. "Erythrophagocytic macrophages have been shown to express heme-oxygenase 1 (HO-1) in human sepsis cases, and inhibit pro-inflammatory cytokine production in cultured mouse bone marrow cells (Slc11a1/Nramp1+/+), thereby suggesting an anti-inflammatory role." (PMID 20195482, 2010).
Arthritis (5 papers, 2014 to 2023). Inflammation of a joint. "The presence of the Slc11a1 R allele, on the other hand, diminished the intensity of macrophage activation, restricting arthritis development." (PMID 30402460, 2018). "The goal of the present work was therefore to discover new PIA QTL using the AIRmax and AIRmin mouse models, and to study the molecular basis underlying Slc11a1 R and S alleles effect in arthritis development through gene expression profiling within these QTL." (PMID 24505471, 2014). "Researchers revealed that SLC11A1 regulates immune-inflammatory genes in macrophages when pristane induces arthritis in mice." (PMID 36531992, 2022). "Our results show that the gene expression profiles of the two arthritis QTL (on chromosomes 5 and 8) correlate with Slc11a1 alleles, resulting in enhanced AIRmaxSS mice susceptibility to PIA." (PMID 24505471, 2014).
bovine tuberculosis (5 papers, 2017 to 2025). "SLC11A1 gene polymorphisms were also associated with tolerance /susceptibility to bovine tuberculosis." (PMID 35737346, 2022). "Likewise, a polymorphism in SLC11A1 was associated to bovine tuberculosis (bTB) resistance while SLC6A6 was suggested to be associated with bTB resistance in Irish Holsteins." (PMID 40660125, 2025). "The knock-in genome editing with the bovine gene natural resistance-associated macrophage protein-1 (NRAMP1), renamed as the functional solute carrier family 11A member 1 gene (SLC11A1), has produced cattle with increased resistance to bovine tuberculosis." (PMID 34869715, 2021).
sarcoidosis (5 papers, 2006 to 2025). Sarcoidosis is a multisystemic disorder of unknown cause characterized by the formation of immune granulomas in involved organs. "Interestingly, susceptibility to Mycobacterium infection is dependent on the polymorphism of the SLC11A1 gene, encoding natural resistance-associated macrophage protein 1; this is also one of the genes associated with an increased risk of sarcoidosis." (PMID 40724571, 2025). "In addition to SLC11A1 and sarcoidosis, polymorphisms of this gene are also found in rheumatoid arthritis, inflammatory bowel disease, multiple sclerosis, and autoimmune diabetes." (PMID 37110254, 2023). "Risk of sarcoidosis is associated with polymorphisms of the SLC11A1 gene." (PMID 37110254, 2023). "Similarly, sarcoidosis has been shown to be associated with particular alleles in BTNL2, IL18, and IFNa, and SLC11A1." (PMID 16608528, 2006). "SLC11A1 has been identified as one of seven genes with increased expression in TB granulomas relative to those formed in sarcoidosis, a non-infectious granulomatous disease." (PMID 40102730, 2025).
Crohn disease (4 papers, 2005 to 2023). A gastrointestinal disorder characterized by chronic inflammation involving all layers of the intestinal wall, noncaseating granulomas affecting the intestinal wall and regional lymph nodes, and transmural fibrosis. "This study did not provide compelling evidence for SLC11A1 disease association; most significantly, there was no apparent evidence of SLC11A1 promoter allele association in the studied Crohn's disease population." (PMID 15757519, 2005).
cutaneous leishmaniasis (4 papers, 2010 to 2025). Leishmaniasis affecting the skin. "There is a need for more SLC11A1 and cutaneous leishmaniasis association studies to help understand the cellular mechanism better." (PMID 28061874, 2017). "This study was designed to investigate genetic variation(s) in SLC11A1 and to assess possible association with cutaneous leishmaniasis in Pakistan." (PMID 28061874, 2017). "Therefore, the current study was designed to determine and analyze the genetic variation(s) in SLC11A1 gene and investigate if these polymorphism(s) are associated with cutaneous leishmaniasis in Pakistan." (PMID 28061874, 2017). "The plot shows pairwise D′ and r2 scores of linkage disequilibrium (LD) between each SNP of SLC11A1 with respect to cutaneous leishmaniasis." (PMID 28061874, 2017). "This study shows that genetic variations in the candidate gene SLC11A1 do not affect susceptibility to cutaneous leishmaniasis in the sample population from Pakistan." (PMID 28061874, 2017). "Association of SLC11A1 with cutaneous leishmaniasis, a neglected tropical disease, is not well established." (PMID 28061874, 2017). "Variations within the SLC11A1 gene were assessed in this study with respect to cutaneous leishmaniasis in Pakistan which has not been reported before from this region." (PMID 28061874, 2017). "This preliminary study was designed to investigate the role of SLC11A1 gene in a Pakistani population infected with cutaneous leishmaniasis which has not been reported before from this region." (PMID 28061874, 2017).
pneumonia (4 papers, 2023 to 2025). An acute, acute and chronic, or chronic inflammation focally or diffusely affecting the lung parenchyma, caused by an infection in one or both of the lungs (by bacteria, viruses, fungi, or mycoplasma.). "In Baladi goats with pneumonia and healthy control group, PCR-DNA sequencing revealed SNPs linked to pneumonia susceptibility and resistance in immunological genes (SLC11A1, CD-14, CCL2, TLR1, TLR7, TLR8, TLR9, defensin, SP110, SPP1, BP1, A2M, ADORA3, CARD15, IRF3, and SCART1)." (PMID 40221769, 2025). "Through PCR-DNA sequencing in Baladi goats with and without pneumonia, SNPs linked to pneumonia susceptibility and resistance were discovered in the immunological (SLC11A1, CD-14, CCL2, TLR1, TLR7, TLR8, TLR9, defensin, SP110, SPP1, BP1, A2M, ADORA3, CARD15, IRF3, and SCART1) genes." (PMID 40711280, 2025). "The immune genes’ mRNA levels in goats (SLC11A1, CD-14, CCL2, TLR1, TLR7, TLR8, TLR9, defensin, SP110, SPP1, BP1, A2M, ADORA3, CARD15, IRF3, and SCART1) varied between the healthy and infected goats with pneumonia." (PMID 40711280, 2025). "The levels of immunological genes (SLC11A1, CD-14, CCL2, TLR1, TLR7, TLR8, TLR9, defensin, SP110, SPP1, BP1, A2M, ADORA3, CARD15, IRF3, and SCART1) vary in goats with and without pneumonia." (PMID 40221769, 2025). "Real-time PCR was conducted to quantify the expression levels of immunological markers (SLC11A1, CD-14, CCL2, TLR1, TLR7, TLR8, TLR9, β defensin, SP110, SPP1, BP1, A2M, ADORA3, CARD15, IRF3, and SCART1) in Baladi goats with and without pneumonia resistance." (PMID 36977224, 2023).
visceral leishmaniasis (4 papers, 2010 to 2019). A severe form of leishmaniasis characterized by irregular bouts of fever, substantial weight loss, swelling of the spleen and liver, and anemia (which may be serious). "A mutation in the SLc11a1 gene, resulting in pump dysfunction, is responsible for the susceptibility of the BALB/c mice to visceral leishmaniasis, raising the hepatic parasitic burden up to 100-fold." (PMID 31882925, 2019). "This means that the mechanism by which SLC11A1 influences CL disease may be different to its influence on visceral leishmaniasis in mice following intravenous needle injection, or in natural infection of dogs and humans, consistent with its many pleiotropic effects." (PMID 20089160, 2010).
asthma (3 papers, 2020 to 2024). "SLC11A1 (NRAMP1) has been shown to be increased in the sputum and serum of patients with asthma, which has been shown to be involved in pathogen resistance, play a role in metal ion transport, and promote anti-microbial pathogen responses." (PMID 39100210, 2024). "The elevated genes include those associated with cellular proliferation (BRICD5), those previously associated with asthma and other inflammatory diseases (IL1RL1, IL6R) and those involved in inflammatory cell signaling (LIME1) and function (SLC11A1)." (PMID 37876037, 2023). "The hypermethylated genes have roles in asthma (VGLL4, AGR2), neurologic development (AGAP1, OTX2), and immune regulation (SCAMP5, SLC11A1)." (PMID 32850550, 2020).
colorectal cancer (3 papers, 2022 to 2025). A primary or metastatic malignant neoplasm that affects the colon or rectum. "Finally, SLC11A1 has been linked to the efficacy of immunotherapy in colorectal cancer." (PMID 41007849, 2025). "It is worth mentioning that SLC11A1 is also a potential biomarker for the prognosis and immunotherapy response in colorectal cancer." (PMID 40129966, 2025).
inflammatory bowel disease (3 papers, 2005 to 2023). A spectrum of small and large bowel inflammatory diseases of unknown etiology. "The aim of this study was to evaluate whether SLC11A1 has a role in the susceptibility to inflammatory bowel disease (IBD) by characterizing a promoter polymorphism within the gene and two short tandem repeat (STR) markers in genetic proximity to SLC11A1." (PMID 15757519, 2005).
Mycobacterium infection (3 papers, 2015 to 2025). Infections with bacteria of the genus Mycobacterium. "A previous study showed that the mRNA level of SLC11A1 increases following Mycobacterium infection in mice." (PMID 26227241, 2015). "In Mycobacterium infections excess iron can overwhelm the Slc11a1 restriction." (PMID 28360906, 2017).
type 2 diabetes mellitus (3 papers, 2022 to 2025). A type of diabetes mellitus that is characterized by insulin resistance or desensitization and increased blood glucose levels. "Consistent with a proinflammatory state, several key cell surface antigens (Cd4, Cd68, Cd84), immune sensors (Cx3cr1, Clec7a), and macrophage genes (Axl, Slc11a1) were upregulated in hIAPP islets and in type 2 diabetes." (PMID 34554282, 2022).
bacteremia (2 papers, 2015 to 2022). "C57BL/6J and BALB/cJ have mutations in solute carrier family 11 member 1 (Slc11a1) and are highly susceptible to fatal STm bacteremia (8, –, 10)." (PMID 35880881, 2022). "Notably, while vaccination protected both Slc11a1+/+ and Slc11a1-/- mice from bacteremia, this protection was lost in P. yoelii-infected mice." (PMID 26366739, 2015).
bladder cancer (2 papers, 2017 to 2022). "SLC11A1 expression has been implicated in bladder cancer recurrence and the response to Calmette–Guerin (BCG) immunotherapy." (PMID 36531992, 2022). "Moreover, SLC11A1 has been proved a correlation with various tumors, such as bladder cancer and esophageal cancer." (PMID 36531992, 2022).
Buruli ulcer (2 papers, 2016 to 2020). "One of these skin specific trans-eQTLs affects SLC11A1, which has been associated with susceptibility to Buruli ulcers." (PMID 27467526, 2016).
esophageal cancer (2 papers, 2021). A primary or metastatic malignant neoplasm involving the esophagus. "SLC11A1 has been shown to be associated with esophageal cancer susceptibility in South African populations." (PMID 34631695, 2021).
gastric cancer (2 papers, 2022). A primary or metastatic malignant neoplasm involving the stomach. "A study constructed a decision tree using mutations in PIK3CA, MEF2C, SLC11A1, and KIF15 to divided patient sub-cohorts with elevated PD-L1 expression, which contribute to identify the novel prognostic biomarkers of Gastric Cancer." (PMID 35359374, 2022).
Kidney Clear Cell Carcinoma (2 papers, 2021 to 2025). "Moreover, SLC11A1 has been suggested to be included in a prognosis signature and used for potential therapeutic drug prediction for renal clear cell carcinoma." (PMID 41007849, 2025).
melanoma (2 papers, 2020 to 2022). A malignant, usually aggressive tumor composed of atypical, neoplastic melanocytes. "In this study, we observed a significant correlation (p≤ 0.05) between the DTH-PPD responses in BCG treated melanoma patients and the four gene SNPs from our panel: IL1β, NRAMP1/SLC11A1, and CXCL12." (PMID 33396862, 2020).
prostate carcinoma (2 papers, 2023). A carcinoma that arises from epithelial cells of the prostate gland. "What is known is that some of these gene products were shown to be implicated in prostate cancer progression, such as, for example, SLC7A5, SLC7A11, SLC11A1, SLC43A1 and SLC1A3." (PMID 36831650, 2023).
Stroke (2 papers, 2024 to 2026). Sudden impairment of blood flow to a part of the brain due to occlusion or rupture of an artery to the brain. "After correction, C1qB remained significantly differentially expressed for both comparisons, while SLC11A1 was only significantly upregulated by microglia nodules in stroke compared to stroke non-nodular WM." (PMID 38396116, 2024). "Microglia nodules compared to non-nodular (NA)WM in MS and in stroke shared only few communally upregulated DE genes (C1qB, RPGR, and SLC11A1), which are associated with involvement in activation of the classical complement pathway and in phagocytosis." (PMID 38396116, 2024).
thyroid cancer (2 papers, 2021 to 2022). "In a data analysis of thyroid cancer, SLC11A1 is associated with macrophages and participates in the construction of a risk model for evaluating the prognosis of thyroid cancer patients." (PMID 36438826, 2022). "When identifying M1 macrophage-related modules related to the prognosis of thyroid cancer by WGCNA, it was found that the 4-gene signature including SLC11A1 and SPP1 could be used to predict the prognosis of patients with thyroid cancer." (PMID 34631695, 2021).
acute promyelocytic leukemia (1 paper, 2013). An aggressive form of acute myeloid leukemia (AML), characterized by arrest of leukocyte differentiation at the promyelocyte stage, due to a specific chromosomal translocation t(15;17) in myeloid cells. "Overall the observed pattern was relatively similar to that of acute promyelocytic leukemia (APL) cells, implying that activation at SLC11A1 locus boundaries occurs early during myeloid development, in accordance with prominent roles for C/EBPβ and PU.1." (PMID 24832660, 2013).